CD9 (CD9 molecule)
Diseases named in the same sentence as CD9 in open-access papers (continued):
Sharing a sentence is not in itself a finding about the gene and the disease.
Hypercalcemia (1 paper, 2018). An abnormally increased calcium concentration in the blood. "Neither decreased Klotho protein nor hypercalcemia was observed in the lung or epithelial cells of CD9/CD81 DKO mice; therefore, it is unlikely that the Klotho protein actively participates in the pathogenesis of DKO mice." (PMID 29572511, 2018).
influenza (1 paper, 2008). An acute viral infection of the respiratory tract, occurring in isolated cases, in epidemics, or in pandemics; it is caused by serologically different strains of viruses (influenzaviruses) designated A, B, and C, has a 3-day incubation period, and usually lasts for 3 to 10 days. "Two members of the tetraspanin family, CD9 and CD81, were found to be associated with influenza virions and are most likely inserted into the viral envelope." (PMID 18535660, 2008).
insulinomas (1 paper, 2017). "Indeed, both ST8SIA1 and CD9 expression were highly variable among both human beta cells as well as insulinomas." (PMID 28974674, 2017). "To determine whether insulinomas are also heterogeneous with respect to the hallmark markers of human beta cell heterogeneity, we explored CD9 and ST8SIA1 expression in our beta cell and insulinoma transcriptome data sets." (PMID 28974674, 2017).
iron deficiency (1 paper, 2025). "Prominent hubs within the network included Cp, Ftl1, CD9, and RACK1, suggesting their central roles in orchestrating the astrocyte response to iron deficiency." (PMID 40590312, 2025).
ischemia (1 paper, 2020). A hypoperfusion of the BLOOD through an organ or tissue caused by a PATHOLOGIC CONSTRICTION or obstruction of its BLOOD VESSELS, or an absence of BLOOD CIRCULATION. "Consistent with the data on NTA, western blot analysis demonstrated that the expression levels of exosome markers CD9 and Flot1 were significant higher in ischemia group, compared to sham control, confirming an increase of exosome release post ischemia." (PMID 32117296, 2020). "Western blot analysis also revealed that CB839 administration significantly suppressed the release of exosomes, ascertained by the reduction of CD9 and Flot1 protein levels in ischemia with CB839 treatment group, compared with that in ischemia with DMSO treatment group." (PMID 32117296, 2020).
keratoconus (1 paper, 2025). A degenerative, structural disorder of the eye, characterized by a cone-shaped protrusion of the cornea. "The results showed a significant decrease in CD63+/CD9+ and CD63+/CD81+/CD9+ expression in male EVs but not in female EVs with keratoconus." (PMID 40643480, 2025).
lentivirus infection (1 paper, 2018). Virus diseases caused by the Lentivirus genus. "CD9 expression increases exosome production and promotes lentivirus infection, thus CD9 could be overexpressed in the engineered cells producing therapeutic exosomes to enhance the yield of exosomes and the delivery efficiency of exosomes." (PMID 30072987, 2018).
leukoplakia (1 paper, 2021). A white patch or plaque on a mucous membrane that cannot be characterized clinically or pathologically as any other disease. "CD9 protein expression was present also in the ductal epithelium and microparticiples in the lumen of small salivary glands located under the leukoplakia." (PMID 34830890, 2021). "CD9 antigen expression in the exosomes of the oral epithelium explained the intercellular flow of SolCD44 and other fluids in the leukoplakia area." (PMID 34830890, 2021). "In oral leukoplakias, CD9 expression was detected in the cell membrane at the same areas as CD44 and in an identical number of epithelial cell layers." (PMID 34830890, 2021). "CD9-positive microareas of the oral epithelium are possibly so-called transport or channel proteins and explain the process of fluid transport inside the oral leukoplakia." (PMID 34830890, 2021). "The second purpose of the parallel examination of CD44 and CD9 proteins was to clarify whether CD9 participates in the transformation processes of oral leukoplakia into cancer." (PMID 34830890, 2021). "Part of the study groups suggested that a reduction in the quantity of CD9 correlates with progression of oral leukoplakia into a malignant process; however, the study of Wang in 2019 concluded that CD9 inhibits the progression of potentially malignant processes." (PMID 34830890, 2021). "Therefore, it is of scientific and clinical interest that we found that both CD44 and CD9 antigens co-expressed in oral mucosa epithelial cell membranes in both healthy mucosa and oral leukoplakia." (PMID 34830890, 2021). "CD9-positive microareas of the oral epithelium may serve as so-called transport or channel proteins, as well as explaining the process of fluid transport inside the oral mucosa and leukoplakia." (PMID 34830890, 2021). "Therefore, the number of biopsies from non-homogeneous leukoplakias for the calculation of CD9- and CD44-positive epithelial layers must be increased in the future." (PMID 34830890, 2021).
lipoma (1 paper, 2020). A benign, usually painless, well-circumscribed lipomatous tumor composed of adipose tissue. "The significant lower levels of CD9 reported in MD-ASC has never been reported in the literature as a feature of lipomas." (PMID 33396896, 2020).
malaria (1 paper, 2023). Malaria is a serious and sometimes fatal disease caused by a parasite that commonly infects a certain type of mosquito which feeds on humans. "CD81 and CD9 were more abundant on plasma sEVs of malaria patients in comparison to healthy controls, while all other 14 proteins were significantly less abundant." (PMID 36961624, 2023). "The signal intensities for capturing sEVs with the antibody cocktail against CD9, CD63, and CD81 and detecting them with unspecific IgG antibodies were similar in the two groups, indicating that the total amounts of released sEVs between malaria and healthy controls were comparable." (PMID 36961624, 2023).
malignant kidney tumors (1 paper, 2021). "In turn, in the 15 WT (out of 17 malignant kidney tumors analyzed) samples, neoplastic cells co-expressed CD9, CD81, and CD271 in the absence of HLADR and GD2, usually in the context of an EpCAM+ (13/15, 86%) phenotype." (PMID 34638431, 2021).
malignant pleural mesothelioma (1 paper, 2013). A malignant neoplasm that arises from mesothelial cells in the pleura and shows a diffuse growth pattern. "We investigated CD9 expression in 112 malignant pleural mesotheliomas." (PMID 23128478, 2013).
Merkel cell carcinoma (1 paper, 2018). "Moreover, in Merkel cell carcinoma cell lines CD9 has mRNA species with differing 5’UTR lengths, with the longer 5’UTR inhibiting ribosome scanning and translation, which may explain the decreased levels of CD9 in Merkel cell carcinoma metastases." (PMID 29416746, 2018).
minimal change disease (1 paper, 2019). "CD9 staining did not reveal glomerular expression in kidney biopsies from healthy controls or patients with proteinuric non-proliferative glomerulonephritis, such as minimal change disease (MCD)." (PMID 31341160, 2019).
myeloid neoplasm (1 paper, 2021). Proliferation of myeloid cells originating from a primitive stem cell. "In myeloid neoplasms, CD9 is involved in the altered interactions between leukemic and stromal cells." (PMID 33918035, 2021). "Finally, the CD9 upregulation in HSCs observed previously in patients affected by myeloid neoplasms could be a reflection of an increase in total CD34+ stem cells, including VSELs, since our study is the first to differentiate the expression of CD9 between the two types of stem cells." (PMID 33918035, 2021). "On the contrary, CD9 appears to be a significant element in leukemic cell development, and its expression is upregulated in CD34+ cells from patients affected by myeloid neoplasms and in multiple myeloma cells." (PMID 33918035, 2021).
myeloproliferative neoplasm (1 paper, 2021). A clonal hematopoietic stem cell disorder, characterized by proliferation in the bone marrow of one or more of the myeloid (i.e., granulocytic, erythroid, megakaryocytic, and mast cell) lineages. "Compared to control VSELs and hematopoietic stem cells (HSCs) from healthy subjects, CD9 is overexpressed in VSELs “like” those isolated from the peripheral blood of patients affected by myeloproliferative neoplasms (MPNs)." (PMID 33918035, 2021). "In addition, we observed, in the phenotypically identical VSELs present in the peripheral blood of patients with myeloproliferative neoplasms, compared to healthy subjects, a significantly higher number of CD9+ cells." (PMID 33918035, 2021).
neuroblastic tumor (1 paper, 2021). A group of nervous system tumors which display neuronal differentiation. "Thus, among neuroblastic tumors, i) CD90, GD2, CD9, and CD56 were the most discriminative between NBL and GNB, whereas ii) CD271, EpCAM, CD9, and CD81 discriminated NBL from PHEO." (PMID 34638431, 2021).
oncocytomas (1 paper, 2009). "However, as more than half of oncocytomas were CD9 positive, the routine use of CD9 to differentiate these two tumor types would be low yield." (PMID 19922654, 2009). "Besides chRCC and a small minority of ccRCC, subsets of unclassified RCC and oncocytomas stained positive for CD9." (PMID 19922654, 2009). "CD9 staining could be marginally helpful in distinguishing between chRCC and oncocytoma, as CD9 negativity was highly specific for oncocytoma as compared to chRCC." (PMID 19922654, 2009).
oral squamous cell carcinoma (1 paper, 2021). "Several studies have analyzed the expression of CD9 in oral squamous cell carcinoma; however, few studies have focused on oral pre-malignant lesions with CD9 antigen expression." (PMID 34830890, 2021). "We found studies on CD9 expression in epithelial dysplasia, and a systematic review from the previous year on extracellular vesicles in oral squamous cell carcinoma and oral potentially malignant disorders." (PMID 34830890, 2021).
orthostatic hypotension (1 paper, 2024). Sudden fall of the blood pressure of at least 20/10 mm Hg when a person stands up. "Finally, although the presence of CD9 in exosomes released by cardiovascular cells has not been established, cholinergic dysfunction in the cardiovascular system can lead to autonomic dysfunction, including orthostatic hypotension, characterized by a drop in blood pressure." (PMID 38384937, 2024).
ovarian tumor (1 paper, 2014). "Conceivably, CD151 may regulate ovarian tumor growth and dissemination, at least in part, by sequestering the function of tumor-promoting molecules such as CD9 and claudin-3 within the TEMM in ovarian tumor cells." (PMID 25356755, 2014).
Parkinson's disease dementia (1 paper, 2024). "Moreover, multiplex analysis of single exosomes from the CSF of Parkinson's disease dementia (PDD) patients via solid-state technology revealed various surface markers, such as CD9, CD63, and CD81." (PMID 39431275, 2024).
penile squamous cell carcinomas (1 paper, 2021). "However, in a previous study of tumor progression in penile squamous cell carcinomas, we observed that invasive tumors have a heterogeneous pattern of CD9 expression, ranging from strong expression in 80% of the cells to a marked loss of CD9 expression in the same case." (PMID 34065085, 2021).
pheochromocytoma (1 paper, 2021). "The only pheochromocytoma analyzed (n = 1) showed a distinct CD56++ CD57+ GD2++ CD271+ CD9+ CD81+ CD90het CD58+ phenotype, in the absence of expression of CD10, CD99, CD117, EpCAM, nuMyoD1, and numyogenin." (PMID 34638431, 2021).
pituitary tumour (1 paper, 2018). "Indeed, we identified CD9-positive cells in a rat model of prolactinoma, the most common pituitary tumour, accompanied by frequent neo-vasculogenesis in the anterior lobe." (PMID 29615783, 2018).
pneumococcal pneumonia (1 paper, 2019). A febrile disease caused by STREPTOCOCCUS PNEUMONIAE. "B1a lymphocytes are suggested to initiate early responses in immune resistance to pneumococcal pneumonia, CS, and DTH, which was herein indirectly confirmed by the enhancement of DTH reaction caused by the flow through fraction of the anti-CD9 column, demonstrated to contain Cas-binding LC." (PMID 31018604, 2019).
polyp (1 paper, 2023). A usually exophytic mass attached to the underlying tissue by a broad base or a thin stalk. "Similar plasma sEV subpopulation compositions were found in CPPs and CRCPs, and a statistically significant difference between polyp and cancer patients was found in the MFI of the CD9/CD24 sEV subpopulation." (PMID 37109070, 2023).
rectal adenocarcinoma (1 paper, 2021). "The impact of NCCR on CD63 and CD9 expression and their prognostic significance in patients with rectal adenocarcinoma is yet to be explored." (PMID 34316329, 2021). "The impact of neoadjuvant concurrent chemoradiation (NCCR) on exosomal markers (CD63 and CD9) expression and their prognostic significance in patients with rectal adenocarcinoma are yet to be explored." (PMID 34316329, 2021). "Using IHC, the exosomal markers (CD63 and CD9) expression increased in patients with rectal adenocarcinoma after treatment with NCCR and thus suggest a possible role of these exosomes in adaptive response to NCCR." (PMID 34316329, 2021).
renal carcinoma (1 paper, 2013). A carcinoma arising from the epithelium of the renal parenchyma or the renal pelvis. "The IHC staining results confirmed the correlations between LGALS8, RAB17 and EpCAM and survival of renal carcinoma patients treated with sunitinib, while CD9 failed to achieve significant discriminatory potential." (PMID 23555683, 2013).
sarcomatoid mesothelioma (1 paper, 2013). A diffuse malignant mesothelioma arising from the pleura and less often the peritoneum. "The biological significance of loss of CD9 expression in sarcomatoid mesothelioma requires further investigation." (PMID 23128478, 2013).
schistosomiasis (1 paper, 2025). An infectious disease caused by parasitic trematodes of the genus Schistosoma that colonize human blood vessels and release eggs that can cause granulomatous reactions leading to acute (swimmer's itch or acute schistosomiasis syndrome) or chronic disease. "In another flatworm infection, schistosomiasis, CD9 has recently been identified as a key surface marker for murine IL-10+ CD19+ Bregs involved in infection progression." (PMID 40725240, 2025).
schwannoma (1 paper, 2025). A benign, usually encapsulated slow growing tumor composed of Schwann cells. "Small extracellular vesicles (sEVs) derived from NF2-associated schwannomas (NF2-EVs) express CD9 and CD81, with a size distribution ranging from 50 to 200 nm." (PMID 41149489, 2025).
scrapie (1 paper, 2010). A fatal disease of the nervous system in sheep and goats, characterized by pruritus, debility, and locomotor incoordination. "Comparing the prp2 morphant with the mouse scrapie model revealed 5 genes in common: GFAP, CD9 antigen (CD9), solute carrier family 14 member 1 (SLC14A1), heat shock 22kDa protein 8 (HSPB8) and syndecan 4 (SDC4)." (PMID 21042590, 2010).
soft tissue sarcoma (1 paper, 2021). A malignant neoplasm arising from muscle tissue, adipose tissue, blood vessels, fibrous tissue, or other supportive tissues excluding the bones. "Among soft tissue sarcomas, CD271, GD2, CD9, and CD90 allowed for the differential diagnosis between EES and RMS, and the CD9, CD81, CD99, and CD271 markers distinguished between OS and CDS." (PMID 34638431, 2021).
tauopathy (1 paper, 2025). Neurodegenerative disorders involving deposition of abnormal tau protein isoforms (tau proteins) in neurons and glial cells in the brain. "In contrast, MG3, prominent in tauopathy mice, exhibits elevated expression of proinflammatory DAM genes such as Apoe, Ctsb, Cd9, and Trem2." (PMID 41331787, 2025).
thrombosis (1 paper, 2021). "Of note, the expression of tetraspanins, namely CD81, CD63, and CD9, and the number/size of the isolated EVs were not significantly different between PV patients with or without thrombosis history (data not shown)." (PMID 34638452, 2021).
triple-negative breast carcinoma (1 paper, 2020). An invasive breast carcinoma which is negative for expression of estrogen receptor (ER), progesterone receptor (PR), and human epidermal growth factor receptor 2 (HER2). "Overexpression of miR-518f-5p led to downregulation of CD9 protein expression in a non-tumorigenic breast cell line and a triple negative breast cancer cell line, resulting in a significant increase in cell migration." (PMID 32224917, 2020).